IL10 (interleukin 10)
Diseases named in the same sentence as IL10 in open-access papers (continued):
Sharing a sentence is not in itself a finding about the gene and the disease.
thymic atrophy (2 papers, 2021). "Collectively, these data suggest that mannans extracted from the flo8 mutant could induce IL-10 production to inhibit C. albicans-induced thymus atrophy by blocking the apoptosis of immature CD4+ CD8+ T cells." (PMID 33154574, 2021).
thymoma (2 papers, 2019 to 2023). A neoplasm arising from the epithelial cells of the thymus. "In our study, the expression of IL-10, as one of the M2-type cytokines, was measured by real-time PCR, which revealed that type B2–3 thymomas exhibited a higher expression of IL-10 than the other types of thymomas did." (PMID 31683962, 2019).
tongue leukoplakia (2 papers, 2019 to 2022). "The expression of immunosuppressive IL-10 is elevated in tongue leukoplakia tissues with high CD163+ macrophage infiltration in the TME; the expression of immunosuppressive IL-10 expression is elevated." (PMID 35740551, 2022). "In tongue leukoplakia, CD163+ macrophages infiltration correlates with immunosuppressive cytokine IL‐10 expression." (PMID 31890299, 2019).
tonsillitis (2 papers, 2016 to 2021). Inflammation of the tonsillar tissue. "IL-10-producing Bregs appear during chronic inflammation (such as tonsillitis) and suppress their progression by downregulating inflammatory cascades associated with IL-1 upregulation." (PMID 26319791, 2016).
transitional cell carcinoma of the bladder (2 papers, 2008 to 2022). "Previous studies validated that CCL2, IL10, CD163, and NRP1 had adverse influence on progression and prognosis of BLCA, while CSF1R antagonist had been used in treatment of urothelial bladder cancers." (PMID 36263004, 2022). "IL-10 is a suppressor of TNF-α synthesis and a potent anti-inflammatory cytokine that is present at the sites of tumors in a wide variety of human cancers, including transitional cell carcinoma of the bladder." (PMID 19040745, 2008).
trichomoniasis (2 papers, 2011 to 2012). An infection that is caused by Trichomonas. "Trichomoniasis appears to be associated with high levels of IL-10 and IL-12; however, that particular study was focused only on HPV infection in the presence of BV as reported in recent study." (PMID 22550593, 2012). "For exampleMIP-1α, VEGF and MPO levels were significantly different than controls inChlamydia and trichomoniasis but not BV while in contrast,IL-6, IL-10, GM-CSF, G-CSF, IL-3, IL-7 and IL-12 were significantly changed inChlamydia and BV but not trichomoniasis." (PMID 21572958, 2011). "Incontrast, IL-12, IL-7, IL-10, IL-3, and IL-4 were increased in BV when comparedto control samples but not in trichomoniasis." (PMID 21572958, 2011).
tuberculous pericarditis (2 papers, 2013 to 2024). "Research has been conducted on the etiology, immune mechanisms, and treatment of tuberculous pericarditis, and showed that IL-10 levels are elevated in the pericardium and blood." (PMID 38455049, 2024). "The most striking finding, however, is the extent to which IL-10 is elevated in serum in effusive-constrictive tuberculous pericarditis, at a ratio of 158 compared to effusive non-constrictive disease." (PMID 24155965, 2013). "Bioactive TGF-β, which was measured in this study, is often very low or undetectable in tuberculous pericarditis which is known to be a delayed type hypersensitivity response driven predominantly by Th-1 cytokines (e.g., IL-10) and characterized by the absence of TGF-β." (PMID 24155965, 2013).
typhoid fever (2 papers, 2011 to 2025). A bacterial infectious disorder contracted by consumption of food or drink contaminated with Salmonella typhi. "In the case of typhoid fever, pro-inflammatory cytokines, including IFN-γ, IL-6, IL-10, TNF-α, and TNF, are also produced in large amounts." (PMID 40014608, 2025). "Indeed, higher levels of IL-10, as well as IL-4, have been detected in PBMC culture of typhoid fever patients when compared to healthy control subjects." (PMID 21829346, 2011).
Ureaplasma infection (2 papers, 2017 to 2023). "Impaired IL-10 responses upon Ureaplasma infection, thus, might predispose to exaggerated or prolonged inflammation." (PMID 29234642, 2017). "Stimulating TNF-α, IL-1β and IL-8 expression, without inducing anti-inflammatory IL-10 and IL-1ra, Ureaplasma infection might push monocyte cytokine responses toward pro-inflammation." (PMID 29234642, 2017).
vaginitis (2 papers, 2016 to 2025). A non-infectious or infectious inflammatory process affecting the vagina. "Moreover, the decrease in the levels of IL-10 in a vaginitis mouse model was reversed by therapeutic treatment." (PMID 39941110, 2025).
ventilator-associated pneumonia (2 papers, 2014 to 2015). Serious INFLAMMATION of the LUNG in patients who required the use of PULMONARY VENTILATOR. "The changes in the mean levels of glutathione peroxidase (GPX) activity, IL-6, IL-8 and IL-10, the incidence of ventilator-associated pneumonia (VAP) and other secondary endpoints were also recorded." (PMID 26429356, 2015).
Ventricular arrhythmia (2 papers, 2024 to 2025). "In the peri-shock period, increased IL-6 and IL-10 serum concentrations and changes in 5-diff blood count (increased neutrophils and decreased eosinophils) are observed, which may be associated with a higher risk of ventricular arrhythmia in HF patients." (PMID 41574188, 2025). "Recently, AAV-mediated expression of IL-10 has been evaluated in a canine model of ventricular arrhythmia, and it has also been shown to decrease inflammatory mediators after intra-articular dosing in an equine inflammatory joint model." (PMID 39703903, 2024).
vitritis (2 papers, 2020 to 2025). "Two patients (5%) experienced progressive disease with active vitritis just after HCT-ASCT (one who was in CR with a normal IL-10 level in the aqueous humour before HCT-ASCT and one with SD and increased IL-10 levels before HCT-ASCT)." (PMID 39562715, 2025). "The patient received a new intravitreal MTX injection that improved the vitritis and normalized the IL-10 level by the 1-month visit." (PMID 33009434, 2020).
xerostomia (2 papers, 2023 to 2026). Dryness of the mouth resulting from reduced salivary secretion. "Among the inflammatory cytokines assessed - IL-6, TNF-α, IFN-γ, IL-10, IL-12p70, IL-1β, IL-8, IL-13, IL-2, IL-5, IL-7 and IL-17A, xerostomia correlated with lower levels of saliva IL-2 and TNF-α, and elevated levels of serum IL-12p70 and IL-10 (p < 0.05)." (PMID 36846089, 2023). "Based on the one-way analysis of variance (ANOVA), the individuals who experienced dry mouth had significantly lower levels of saliva IL-2 and TNF-α, and higher levels of serum IL-12p70 and IL-10." (PMID 36846089, 2023). "We found that saliva IL-2 and TNF-α levels were lower, and serum IL-12p70 and IL-10 (p < 0.05) higher in patients with xerostomia than those without." (PMID 36846089, 2023).
Acanthamoeba infection (1 paper, 2025). "Several cytokines, such as interferon-gamma (IFN-γ), interleukin (IL)-4, IL-10, IL-17A, IL-17F, and IL-22, are rapidly produced and secreted in response to Acanthamoeba infection." (PMID 40109888, 2025). "Several cytokines, for example, IFN-γ, IL-4, IL-10, IL-17A, IL-17F, and IL-22, were reported to rapidly produce and secrete in response to the Acanthamoeba infection but not IL-1β cytokine." (PMID 40109888, 2025).
acral melanoma (1 paper, 2022). "IL-5 and IL-10 were positively associated with a low QOL in non-acral melanoma TNM stage II to IV." (PMID 36405903, 2022).
actinomycetoma (1 paper, 2013). "Increased IL-10 cytokine levels have also been detected in mycetoma lesions as well as in animal models of actinomycetoma caused by Nocardia brasiliensis." (PMID 23717704, 2013).
Acute encephalopathy (1 paper, 2018). "Some studies have shown that serum IL-6, IL-10, and TNF-α levels were elevated in KD, and these cytokines could cause brain damage in acute encephalopathy following prolonged febrile seizures." (PMID 31922014, 2018).
adenovirus infection (1 paper, 2020). "Whether high levels of IL-6 and IL-10 in patients with adenovirus infection contribute the worse outcome warrants further investigation." (PMID 32772917, 2020).
Adrenal insufficiency (1 paper, 2018). Insufficient production of steroid hormones (primarily cortisol) by the adrenal glands. "SND increased overall survival rate within 4 days and attenuated adrenal insufficiency in septic rats by downregulating TLR4 mRNA and protein expression in adrenal tissue, inhibiting adrenal production of TNF-α and IL-10, and improving adrenal responsiveness." (PMID 30018657, 2018).
aging (1 paper, 2021). A developmental process that is a deterioration and loss of function over time. "We next investigated whether pESM supplementation could ameliorate skin aging in IL-10 KO mice." (PMID 34206704, 2021).
alcoholic fatty liver disease (1 paper, 2018). Lipid infiltration of the hepatic parenchymal cells that is due to alcohol abuse. "In line, morbidly obese patients with NASH have higher intrahepatic gene expression of Th1-associated genes and a decreased ratio of IL-10/IFNy as compared to patients with non-alcoholic fatty liver disease." (PMID 30619297, 2018).
alexithymia (1 paper, 2021). An agnosia that is a deficiency in understanding, processing, or describing emotions. "Lymphocyte subset counts (CD4, CD8), in vitro production of interleukin 1β (IL-1β), IL-2, IL-4, and IL-10 by phytohemagglutinin stimulated peripheral blood lymphocytes, as well as serum cortisol levels, were compared between women with and without alexithymia." (PMID 34987425, 2021).
Alopecia universalis (1 paper, 2024). Alopecia universalis is the most severe form of alopecia areata, an inflammatory disease of the hair follicle, which is characterized by a complete loss of hair of the scalp and all the hair-bearing areas of the body. "Another case report described a paradoxical increase in cytokines, including IL-4, IL-6, IL-10, IFN-γ, and IL-17, after six months of Tofacitinib treatment in a patient with alopecia universalis." (PMID 39850156, 2024).
amyloidoma (1 paper, 2024). Nodular localized form of amyloidosis with predominantly thoracic localization (pulmonary amyloidosis), considered as secondary protein structure disease in which insoluble protein fibrils accumulate extracellularly. "ALλ(CLA) amyloidomas contained significantly more CXCL10, GM-CSF (granulocyte monocyte-colony stimulating factor), and IL-10, with more expression of CCL5 trending towards significance (p=0.0882)." (PMID 39600710, 2024).
anal prolapse (1 paper, 2022). "Reduces anal prolapse, surrounding hyperemia by decreasing MPO activity, serum IL-1β, IL-6, TNF-α levels, and increasing IL-4, IL-10 levels." (PMID 35548468, 2022).
anaplasmosis (1 paper, 2024). "A key anti-inflammatory cytokine IL-10 is produced following experimental and clinical anaplasmosis and ehrlichiosis, and it has been linked to suppression of Th1 cell-mediated immunity during infection by inhibition of IFN-γ secretion via phagocytic cells." (PMID 39770719, 2024). "In addition, the differences in circulating IL-10 between groups of Anaplasmosis dogs and groups with mixed infection are with borderline significance (28.34 ± 8.32 vs. 66.62 ± 25.11; p = 0.053)." (PMID 39770719, 2024).
angioimmunoblastic T-cell lymphoma (1 paper, 2017). A mature T-cell non-Hodgkin lymphoma, characterized by systemic disease and a polymorphous infiltrate involving lymph nodes and extranodal sites. "The aim of this study was to evaluate whether serum IL-10 level at diagnosis and tissue infiltration of M2 macrophages could predict survival outcome of patients with angioimmunoblastic T-cell lymphoma (AITL)." (PMID 29100307, 2017).
anorexia nervosa (1 paper, 2019). A disorder most often seen in adolescent females characterized by a refusal to maintain a minimally normal body weight, an intense fear of gaining weight, a disturbance in body image, and, in postmenarcheal females, the development of amenorrhea. "IL-1α, IL-10, EGF, and IFN-γ were altered individuals with anorexia nervosa (AN) and binge eating disorder (BED)." (PMID 31450770, 2019).
anthrax (1 paper, 2015). "Thus, cutaneous anthrax induces a broad T cell memory response characterized not only by the presence of Th1 cytokines IFNγ and TNFα, but also Th2 (IL-5 and IL-13), Th17 (IL-17/IL-22), Th22 (IL-22) and Th9 (IL-9) cytokines and a potentially regulatory IL-10 response." (PMID 26075052, 2015).
anxiety-depression (1 paper, 2013). "The levels of IL-1β and IL-10 in the sigmoid colon mucosal membranes and blood of the anxiety-depression IBS-D group were significantly different from those of the non-anxiety-depression IBS group." (PMID 23935726, 2013).
aortic stenosis (1 paper, 2015). Aortic valve stenosis is a aortic valve disease caused by the incomplete opening of the aortic valve. "Moreover, several related studies have demonstrated that polymorphisms in the IL-10 gene have an impact on the patients with severe aortic stenosis undergoing aortic valve replacement surgery in Germans and Canadians." (PMID 26039365, 2015).
Apathy (1 paper, 2022). Apathy is a quantitative reduction of interest, motivation and the initiation and persistence of goal-directed behavior, where often the accompanying emotions, thoughts, and social interactions are also diminished. "Among AD patients, compared with those without apathy, those with apathy had higher levels of interleukin-6, interleukin-10, and leptin." (PMID 36572691, 2022).
Aphasia (1 paper, 2025). An acquired language impairment of some or all of the abilities to produce or comprehend speech and to read or write. "The relationship between cardiovascular disease history, treatment window, intraoperative blood loss, thrombectomy time, neutrophil percentage, aphasia symptoms, CRP, IL-6, IL-10 and recurrence degree is not significant." (PMID 40917676, 2025).
aphthous stomatitis (1 paper, 2022). "Key words:Recurrent aphthous stomatitis, aphthae, IL-10, TGF-β, gene polymorphisms, oral mucosa." (PMID 35660731, 2022).
asthenia (1 paper, 2020). Clinical sign or symptom manifested as debility, or lack or loss of strength and energy. "THD has synergistic and additive antiemetic, anti-asthenia, and analgesic effects of corticosteroids 57, 58; it inhibits the expression of cytokines without affecting levels of IL-2, IL-4, and IL-10 59, 60, thus offering the possibility of steroid-sparing or steroid-replacement therapy." (PMID 32489473, 2020).
atopic march (1 paper, 2023). sequential manifestations of different allergic diseases such as eczema, asthma and rhinitis. "In particular, the T helpers 2 (Th2) subset, through its cytokine signatures made of interleukins (ILs), such as IL-4, IL-5, IL-10, and IL-13, as well as mast cells and their related histamine pathways, contribute greatly to the perpetuation and evolution of the atopic march." (PMID 36675006, 2023).
autoimmune peripheral neuropathies (1 paper, 2024). "All those data suggest an unexpected pathogenic role for IL-10 in autoimmune peripheral neuropathies." (PMID 37638717, 2024).
Autosomal dominant hyper-IgE syndrome (1 paper, 2018). 2000 IU/ml), recurring staphylococcal skin abscesses, and recurrent pneumonia with formation of pneumatoceles. "In other experiments, PBMCs isolated from healthy donors or from autosomal dominant hyper-IgE syndrome (STAT3 loss-of-function) subjects were cultured with combinations of IL-4 and IL-10." (PMID 31026808, 2018). "PBMCs from autosomal dominant hyper-IgE syndrome individuals failed to consistently modulate IgE production in response to IL-4 and IL-10." (PMID 31026808, 2018).
B-cell lymphoblastic leukemia (1 paper, 2024). "In studies, patients with B-cell lymphoblastic leukemia following CAR-T cell therapy presented elevated levels of IL-1α, IL-2, IL-3, IL-5, IL-6, IL-8 IL-10, IL-15, IFN- γ, procalcitonin, CRP, G-CSF, GM-CSF, and MCP-1, and their levels were linked to the severity of neurotoxicity." (PMID 39409959, 2024).
Bell's palsy (1 paper, 2021). Partial or complete paralysis of the facial muscles of one side of a person's face. "This investigation was a cross-sectional study aimed at determining Interleukin-10 serum levels in the acute phase of Bell’s palsy and evaluating its interrelation with the severity of abnormalities settled in the nerve conduction study." (PMID 35474925, 2021). "The role of Interleukin-10 (IL-10) in Bell’s palsy is yet unknown, and few studies have shed light on the matter." (PMID 35474925, 2021). "Therefore, the serum level of IL-10 cannot surrogate the NCS test for evaluating the severity of acute Bell’s palsy." (PMID 35474925, 2021). "The role of Interleukin 10 (IL10) in Bell’s palsy is yet unknown." (PMID 35474925, 2021). "The IL-10 serum levels are not relevant to the pathology of Bell’s palsy, and the assessment of IL-10 serum levels cannot be used as an alternative to NCS for evaluating the severity of acute Bell’s palsy." (PMID 35474925, 2021). "Thus, serum levels of IL-10 could not be recommended as a tool for choosing a therapeutic approach, and it is not appropriate for early diagnostic confirmation and differential diagnosis of Bell’s palsy." (PMID 35474925, 2021). "The role of IL-10 in Bell’s palsy is unknown, and there have not been any studies done hereupon." (PMID 35474925, 2021). "This cross-sectional study demonstrates that no meaningful relation exists between IL-10 serum levels and neural damage severity (based on NCS) in Bell’s palsy." (PMID 35474925, 2021).
biliary tract cancer (1 paper, 2014). "Although the IgG4 reaction in biliary tract cancers and IgG4-SC are closely associated with the IL-10 regulatory cytokine milieu, it is possible that both mechanisms are specific for cancer tissues but different from IgG4-related pathogenesis." (PMID 25132998, 2014). "These biliary tract cancer cells could act as nonprofessional APCs by generating IL-10-producing regulatory T cells (anergy T cells)." (PMID 25132998, 2014).
bone marrow failure (1 paper, 2020). "As for IL-10, Rapa can increase the secretion of IL-10 from Treg cells compared with CsA group, and had a better outcome when combined with Elt in bone marrow failure mice." (PMID 33123600, 2020).
brain glioma (1 paper, 2025). A malignant glioma that involves the brain. "In solid tumors, the involvement of IL-10 is complex in its interaction with tumor cells, and it has been suggested that elevated serum levels of IL-10 and other markers in patients with brain glioma could be a valuable prognostic indicator." (PMID 40722593, 2025).
bronchopneumonia (1 paper, 2017). Acute inflammation of the walls of the terminal bronchioles that spreads into the peribronchial alveoli and alveolar ducts. "The role of IL-10 during CPXV infection is probably beneficial for the virus, and IL-10 suppresses immunopathology in the lungs because IL-10-deficient mice after re-challenge with CPXV displayed greater bronchopneumonia than wild-type mice." (PMID 29312229, 2017).
burn (1 paper, 2012). A traumatic injury involving interruption of tissue cohesiveness that results from exposure to caustic chemicals, extreme heat, extreme cold or excessive radiation. "Increased levels of IL-1α, IL-2, IL-4, IL-10, IFN-γ and TNFα could be detected in culture media of burn injury skin cultures." (PMID 22359539, 2012).
cardia cancer (1 paper, 2020). A malignant neoplasm involving the cardia of stomach. "Locally, cardia cancers were distinguished by comparatively high expression of NOS2, and tended to have seven-fold higher expression of IL10, which correlated positively with histological grade and, thus, with tumor aggressiveness." (PMID 32630408, 2020).
cat-scratch disease (1 paper, 2025). Cat scratch disease is an infectious illness caused by the bacteria bartonella (Bartonella henselae). "Bartonella hensalae, which causes cat scratch disease in humans, employs the effector BepD to activate STAT3 in a c-Abl kinase-dependent mechanism to suppress tumor necrosis factor-α signaling and stimulate IL-10 production." (PMID 40188438, 2025).